IL11 (interleukin 11)
Diseases named in the same sentence as IL11 in open-access papers (continued):
Sharing a sentence is not in itself a finding about the gene and the disease.
prostate carcinoma (13 papers, 2007 to 2025). A carcinoma that arises from epithelial cells of the prostate gland. "Subsequently, we introduced prostate cancer cells with stable IL-11 knockdown and cells with concurrent docetaxel treatment into a murine model." (PMID 38429845, 2024). "This synergistic relationship not only reinforces the contributory role of IL-11/IL-11RA signalling in chemoresistance but also showcases the potential of targeted therapies to improve clinical outcomes in prostate cancer." (PMID 38429845, 2024). "In our investigation into the role of IL-11 in prostate cancer signalling pathways, we employed a multifaceted analytical approach." (PMID 38429845, 2024). "To ascertain the impact of interleukin-11 (IL-11) on the phenotypic attributes of prostate cancer cell lines, we conducted a series of experiments on PC3 and DU145 cells." (PMID 38429845, 2024). "In aggregate, these data highlight the pivotal role of IL-11 in facilitating prostate cancer cell proliferation and tumour growth and underscore the therapeutic potential of targeting IL-11 in conjunction with established chemotherapy regimens." (PMID 38429845, 2024). "This enrichment was evident across a spectrum of genes ranked according to their expression profiles in prostate cancer cell lines, signifying the pathway's active role in response to IL-11." (PMID 38429845, 2024). "Intrigued by the nexus between cytokine signalling and transcriptional control, we postulate that the IL-11 autocrine loop is a determinant of docetaxel resistance in prostate cancer via the JAK1/STAT4 signalling axis." (PMID 38429845, 2024). "Utilizing single-cell sequencing data from docetaxel-resistant prostate cancer organoids, we identified the exocrine factor IL-11 as being significantly overexpressed in resistant prostate cancer." (PMID 38429845, 2024). "Abnormal STAT3 activation in prostate cancer cells is linked to EGF receptor and JAK kinase-mediated trafficking of IL-6 and IL-11 cytokines." (PMID 36852795, 2023). "The results are in line with our present study showing that IL-6 and IL-11 stimulated the stemness of prostate cancer cells in vitro." (PMID 26528857, 2015). "Through direct selection of peptide libraries in patients, we isolated a ligand peptide mimicking IL-11 from the prostate vasculature and proposed the IL-11Rα as a target during the progression of prostate cancer." (PMID 18941632, 2008). "Frequent amplification of IL11-RA in prostate cancer is a potential mechanism of IL11-RA overexpression in this tumor type." (PMID 17712417, 2007). "Screening of 20 primary prostate carcinomas by qPCR revealed an IL11-RA copy number gain in 75% of the tumors analyzed." (PMID 17712417, 2007). "Moreover, a protein‒protein interaction network explicitly centred around IL-11 revealed extensive interactions, with network density suggesting a prominent regulatory role for IL-11 in the signalling milieu of prostate cancer." (PMID 38429845, 2024). "Autocrine secretion of IL-11 was markedly increased in docetaxel-resistant prostate cancer cells." (PMID 38429845, 2024). "The potential to overcome resistance by inhibiting the IL-11/IL-11RA/JAK1/STAT4 axis may represent a paradigm shift in prostate cancer treatment." (PMID 38429845, 2024). "We further evaluated the compensatory effects of STAT4 overexpression in prostate cancer cell lines PC3 and DU145 with reduced IL-11 signalling." (PMID 38429845, 2024). "In the prostate cancer cell lines PC3 and DU145, IL-11 treatment significantly increased levels of phosphorylated STAT4, indicative of its activation." (PMID 38429845, 2024). "LIM domain only 2 (LMO2) was put forward as a new marker in prostate cancer, which increases the viability of prostate cancer cells via releasing FGF-9 and IL-11 from prostate fibroblasts." (PMID 36865499, 2023). "Previous research has demonstrated the IL11/IL11RA axis was activated under hypoxia and promoted the proliferation of prostate cancer cells." (PMID 33197880, 2020).
prostate carcinoma (continued). "Parallel changes were noted in STAT family proteins, with STAT4 in particular demonstrating a significant response to IL-11 modulation, thereby reinforcing the connection between IL-11 signalling and STAT4-mediated transcriptional regulation in prostate cancer." (PMID 38429845, 2024). "Additionally, our analysis of clinical PCA samples revealed a marked overexpression of IL-11 and IL-11RA in prostate cancer tissues versus adjacent non-cancerous tissues." (PMID 38429845, 2024). "Notably, upon neutralization of IL-11 signalling using an IL-11 antagonist, the expression and phosphorylation levels of JAK1 and STAT4 were markedly altered, substantiating the pivotal role of IL-11 in activation of the JAK/STAT pathway in prostate cancer." (PMID 38429845, 2024). "Additionally, the data revealed that recombinant human IL-11 (Rh IL-11) exerted a cytoprotective effect against a range of DTX concentrations, indicating a potential mechanism by which IL-11 confers a survival benefit to prostate cancer cells." (PMID 38429845, 2024).
breast tumor (12 papers, 2010 to 2024). "For example, miR-206 was reported to repress stemness and metastasis of breast tumor cells by affecting the MKL1/IL-11 cascade." (PMID 35184640, 2022). "As breast tumour cells are able to lead to bone disruption, when they grow in the bone metastatic site, several studies have considered the contribution of IL-11 in this condition." (PMID 34201209, 2021). "Several studies have demonstrated that breast tumour cells can also target osteoblasts to stimulate the production of IL-11, further increasing IL-11 concentrations in the bone microenvironment." (PMID 34201209, 2021). "Notably, several studies have demonstrated that breast tumor cells can also target osteoblasts to stimulate their production of IL-11, further increasing IL-11 concentrations in the bone microenvironment." (PMID 23311882, 2013). "Silencing of HS6ST2 reduced the transcriptional activity mediated by Smad2/3/4, thereby inhibiting the production of IL-11 induced by TGF-β, resulting in the inhibition of breast tumor growth." (PMID 37932473, 2023). "To explore the clinical significance of the MITR (HDAC9)/MEF2A/IL11 axis in TNBCs, we performed immunohistochemical (IHC) analyses on 44 primary breast tumors and 4 noncancerous mammary controls with the MITR antibody." (PMID 33042272, 2020). "An example of a known metastasis virulence genes that does not contribute to primary tumour growth is interleukin-11, which promotes breast tumour metastasis to the bone but does not provide any advantage to the primary tumour." (PMID 26052355, 2015).
endometrial cancer (12 papers, 2010 to 2025). Primary or metastatic malignant neoplasm involving the endometrium (mucous membrane that lines the endometrial cavity). "Loss of miR-1 expression in primary type I human endometrial cancer correlates with elevated IL11 expression." (PMID 28186993, 2017). "The present study suggests that IL11 in uterine washings may be useful as a diagnostic marker for early stage endometrial cancer." (PMID 20553623, 2010). "Large scale studies are required to determine whether IL11 in uterine washings may be useful as a diagnostic marker for endometrial cancer." (PMID 20553623, 2010). "As a result of these findings, human monoclonal antibodies have been developed against IL-11 with success in treating some cancers, including endometrial cancer." (PMID 38248304, 2024). "In a study determining the role of IL-11 signalling in endometrial cancers, the addition of IL-11 resulted in a migratory increase of 50%." (PMID 38248304, 2024). "IL-11 regulates endometrial cancer cell adhesion and migration via upregulating the phosphorylated (p)-STAT3 protein abundance." (PMID 37153732, 2023). "So, again, this is an example of indirect role of IL-11 in endometrial cancer progression via CSPG4." (PMID 34951691, 2022). "Silencing CSPG4 gene expression decreased endometrial cancer cell proliferation; this is an example of indirect role of IL-11 in endometrial cancer progression via CSPG4." (PMID 34951691, 2022). "We and others previously determined that IL11 mRNA and protein are up-regulated in endometrial tumour tissue and uterine lavage in women and we have shown that IL11 alters endometrial cancer cell function in vitro, via STAT3." (PMID 28186993, 2017). "In women with endometrial cancer, IL11 levels are elevated in uterine lavage fluid and is positively associated with increasing endometrial tumour grade." (PMID 28186993, 2017). "What’s more, LAY reported that interleukin 11 regulated endometrial cancer cell adhesion and migration via STAT3102, and L1 cell adhesion molecule is a strong predictor for distant recurrence and overall survival in early stage endometrial cancer." (PMID 26373443, 2015). "In the current study, we determined the levels of IL11 in uterine lavage in women with endometrial cancer and postmenopausal controls." (PMID 20553623, 2010). "It is also the first study to demonstrate that IL11 protein is upregulated in Grade 1 endometrial cancers compared to postmenopausal endometrial epithelium and suggests that IL11 signalling is active in endometrial cancer cells." (PMID 20553623, 2010). "It further aimed to determine the levels of IL11 protein and its signaling molecules in human endometrial cancer of varying grades, and endometrium from postmenopausal women and IL11 signalling mechanisms in endometrial cancer cell lines." (PMID 20553623, 2010). "IL11 mRNA was reported to be higher in endometrial cancer tissue compared to endometrial tissue from proliferative phase tissue, while differences in the level of IL11 protein between the groups was not reported." (PMID 20553623, 2010). "Functional studies are required to elucidate the role of IL11 in tumourigenesis and determine its potential as a prognostic marker and therapeutic target for endometrial cancer." (PMID 20553623, 2010). "In agreement with the present study, IL11 is significantly upregulated in several non-endometrial cancers." (PMID 20553623, 2010). "This study aimed to determine the levels of IL11 in uterine lavage fluid in women with endometrial cancer and postmenopausal women." (PMID 20553623, 2010). "This study was the first to show that IL11 protein was increased in uterine fluid and endometrial tumour epithelial cells in women with Grade 1 endometrial carcinoma compared to postmenopausal women." (PMID 20553623, 2010). "Increased expression of IL11 has been found in endometrial cancer compared with normal endometrium, but its function in this cancer is still unknown." (PMID 36982551, 2023).
endometrial cancer (continued). "IL-11 treatment resulted in a 50% increase in cell migration in AN3CA endometrial cancer cells." (PMID 34951691, 2022). "We have previously demonstrated that IL11 promotes endometrial cancer cell migration in vitro, via STAT3 and that blockade of IL11 receptor (R) α reduces grade-1 and grade-2 derived human endometrial epithelial cell line xenograft tumour growth and metastasis in mouse models." (PMID 28186993, 2017). "The consequences of this reduced sensitivity could be that IL11 signalling is unregulated in endometrial cancer cells." (PMID 20553623, 2010). "Our study suggests that IL11 in uterine washings may be useful as an early marker of endometrial cancer." (PMID 20553623, 2010). "The precise role of IL11 in endometrial cancer remains to be elucidated." (PMID 20553623, 2010). "It remains to be determined whether IL11 similarly regulates tumour cell adhesion, migration and invasion in endometrial cancers." (PMID 20553623, 2010). "However, since endometrial cancer affects predominantly post-menopausal women, we compared the levels of IL11, IL11Rα, pSTAT3 and SOCS3 in endometrial cancer tissue to endometrial tissue from post-menopausal." (PMID 20553623, 2010). "Whether IL11 alone activates STAT3 phosphorylation in endometrial cancer cells remains to be elucidated." (PMID 20553623, 2010). "This suggests that IL11 levels in uterine washings may be useful as an endometrial cancer marker." (PMID 20553623, 2010). "And in endometrial cancer, YAP enhances cell proliferation, migration, and invasion by upregulating interleukin-11 (IL-11) transcription through p65, exacerbating the malignancy." (PMID 40673277, 2025). "IL-6, Il-11, IL-31, IL-33, TNF-α, TGF-β1, SDF-1 and CXCR are involved in endometrial cancer cell growth and metastasis or involved in epithelial mesenchymal transformation (EMT) or associated with advanced disease." (PMID 34951691, 2022). "By contrast IL11 weakly stimulated SOCS3 protein at 100 ng/ml in the carcinoma HEC-1A and Ishikawa cells possibly suggesting reduced sensitivity in endometrial cancer cells." (PMID 20553623, 2010). "It further demonstrated that IL11's main endometrial signalling molecules, pSTAT3 and SOCS3, were produced by endometrial cancer cells." (PMID 20553623, 2010). "The endometrial cancer cell lines ECC-1, HEC-1A and Ishikawa and or HES cells were treated with diluents control, IL11 (1, 10, 100, 500 ng/ml) for 15 minutes or 4 hours." (PMID 20553623, 2010). "By contrast, IL11 stimulated pSTAT3 from 1-10 ng/ml in HEC-1A and 1 ng/ml in Ishikawa endometrial carcinoma cells respectively compared to diluent control treated cells." (PMID 20553623, 2010). "We compared IL11, IL11Rα, pSTAT3 and SOCS3 protein in human endometrial carcinomas of varying histologic grades with endometrium from postmenopausal and cycling women." (PMID 20553623, 2010). "It indicates that IL11, along with its specific receptor, IL11Rα, and downstream signalling molecules, STAT3 and SOCS3, are likely to play a role in the progression of endometrial carcinoma." (PMID 20553623, 2010). "The present study suggests that IL11, along with its specific receptor and downstream signalling molecules pSTAT3 and SOCS3, are likely to play a complex role in the progression of endometrial carcinoma." (PMID 20553623, 2010). "In gene knockout experiment with small interfering-YAP (si-YAP), addition of si-YAP suppressed proliferation of endometrial cancer cells and decreased the expression of IL-6 and IL-11, which proves that YAP induces IL-6 and IL-11 which in turn promotes cell proliferation." (PMID 34951691, 2022). "Overall, all the human endometrial cancer cell lines (ECC-1: 5 pg/106 cells, HEC-1A: 3 pg/106 cells, Ishikawa cells: 6 pg/106 cells) and the endometrial epithelial cell line HES, secreted very low levels of IL11 under serum free conditions." (PMID 20553623, 2010).
endometrial cancer (continued). "It is also not knownswhether IL11 downstream signalling is active in endometrial cancer, which would suggest a role for IL11 in carcinogenesis." (PMID 20553623, 2010). "IL11 was shown to signal via pSTAT3 and SOCS3 in human endometrial cancer cell lines." (PMID 20553623, 2010). "A recent study had identified that IL11 and IL11Rα are expressed in endometrial cancer, although there are no studies comparing the levels of IL11 protein in endometrial cancer and postmenopausal women in whom the vast majority of endometrial cancers develop." (PMID 20553623, 2010). "We determined the effect of IL11 on its downstream signaling molecules in endometrial cancer and non-cancer endometrial epithelial cells." (PMID 20553623, 2010). "In the human endometrium and placenta, IL11 activates the janus kinase and signal transducers and activators of transcription (JAK/STAT3) pathway STAT3 is constitutively active in many human cancers, including endometrial cancer and has the capacity to promote epithelial tumour growth." (PMID 28186993, 2017). "However, the regulation and function of IL11 in high grade endometrial cancer cell has not been fully evaluated." (PMID 28186993, 2017). "The effect of IL11 on pSTAT3/STAT3 and SOCS3 protein abundance in endometrial cancer cell lines and non-cancer endometrial epithelial cells was determined by Western blot." (PMID 20553623, 2010). "IL11, IL11 receptor(R) α, phosphorylated (p) STAT3 and SOCS3 were examined by immunohistochemistry in endometrial carcinomas and in control endometrium from postmenopausal women and normal cycling women." (PMID 20553623, 2010).
lung disease (12 papers, 2020 to 2025). "In conclusion, we suggest that IL11 causes lung pathology in severe lung disease through at least two pathological processes." (PMID 39358385, 2024). "The JAK/STAT pathway is activated by a variety of pro-inflammatory cytokines, such as IL-6, IL-11, and IL-13, which are upregulated in different lung diseases." (PMID 36793900, 2023). "With the emergence of new roles for IL-6 family cytokines in disease and, in particular, roles of IL-11 in cardiovascular disease, lung disease, and cancer, there is an emerging need to develop therapeutics that can progress to clinical use." (PMID 32765502, 2020). "In certain disease models, IL11 upregulation is associated with enhanced pro-inflammatory responses—for example, in fibrotic lung disease, as well as cardiac and hepatic disorders, IL11 activates stromal cells, promotes immune cell recruitment, and sustains chronic inflammation." (PMID 41487426, 2025). "We further explored the regulation of IL‐11 by iNOS studying HPSPF patient‐derived primary lung fibroblasts and lung fibroblasts from controls unaffected by lung disease." (PMID 34323400, 2021). "The expression pattern of IL-11 in human pulmonary diseases is intriguing but does not reveal whether IL-11 upregulation is a protective or a disease-causing mechanism." (PMID 33262481, 2020).